LIN7A (lin-7 cell polarity scaffold A)
Description:
Plays a role in establishing and maintaining the asymmetric distribution of channels and receptors at the plasma membrane of polarized cells. Forms membrane-associated multiprotein complexes that may regulate delivery and recycling of proteins to the correct membrane domains. The tripartite complex composed of LIN7 (LIN7A, LIN7B or LIN7C), CASK and APBA1 associates with the motor protein KIF17 to transport vesicles containing N-methyl-D-aspartate (NMDA) receptor subunit NR2B along microtubules (By similarity). This complex may have the potential to couple synaptic vesicle exocytosis to cell adhesion in brain. Ensures the proper localization of GRIN2B (subunit 2B of the NMDA receptor) to neuronal postsynaptic density and may function in localizing synaptic vesicles at synapses where it is recruited by beta-catenin and cadherin. Required to localize Kir2 channels, GABA transporter (SLC6A12) and EGFR/ERBB1, ERBB2, ERBB3 and ERBB4 to the basolateral membrane of epithelial cells.
Synonyms: Lin-7A; MALS-1; TIP-33; MALS1; VELI1; LIN7
Tractability: Antibody: its Gene Ontology location is reachable by antibodies, with high confidence; UniProt places it where antibodies can reach, with medium confidence. PROTAC: ubiquitination databases record sites on it; its protein half-life has been measured.
Gene: Protein-coding gene on chromosome 12 (80,792,520 to 80,937,934, reverse strand). Ensembl gene ENSG00000111052.
Subcellular location: Cell membrane; Basolateral cell membrane; Cell junction; Postsynaptic density membrane; Cell junction, tight junction
Pathways (Reactome):
Neuronal System: Assembly and cell surface presentation of NMDA receptors; Dopamine Neurotransmitter Release Cycle; Neurexins and neuroligins
Gene Ontology:
Molecular function: L27 domain binding; protein binding; protein-macromolecule adaptor activity
Biological process: exocytosis; neurotransmitter secretion; protein transport; protein-containing complex assembly; regulation of synaptic assembly at neuromuscular junction; synaptic vesicle transport
Cellular component: extracellular exosome; anchoring junction; basolateral plasma membrane; cell-cell junction; membrane; MPP7-DLG1-LIN7 complex; plasma membrane; postsynaptic density membrane; synapse; bicellular tight junction; presynapse
Genetic constraint (gnomAD): Loss-of-function variants: 15 observed, 16.72 expected, observed/expected ratio (o/e) 0.9, 90% interval 0.6 to 1.38. The upper end of that interval is the gene's LOEUF score, 1.38, which puts it in group 5 of 6, group 1 being the genes least tolerant of losing a copy. Missense variants: 173 observed, 204.01 expected, observed/expected ratio (o/e) 0.85, 90% interval 0.75 to 0.96. Synonymous variants: 92 observed, 78.73 expected, observed/expected ratio (o/e) 1.17, 90% interval 0.99 to 1.39.
Homologues: Orthologues: chimpanzee LIN7A (100% identical), macaque LIN7A (100% identical), rabbit LIN7A (100% identical), mouse Lin7a (99% identical), pig LIN7A (99% identical), dog LIN7A (99% identical), tropical clawed frog lin7a (92% identical), guinea pig LIN7A (88% identical), zebrafish lin7a (88% identical), rat Lin7a (73% identical), Drosophila melanogaster veli (64% identical), Caenorhabditis elegans lin-7 (57% identical). Paralogues in human: LIN7C (67% identical), LIN7B (67% identical), PDZD11 (22% identical).
Diseases named in the same sentence as LIN7A in open-access papers:
LIN7A is named in the same sentence as 27 diseases in open-access papers, as found by Europe PMC text mining. Sharing a sentence is not in itself a finding about the gene and the disease. The quoted sentences say what the papers report.
hepatocellular carcinoma (5 papers, 2018 to 2025). A malignant tumor that arises from hepatocytes. "However, increased LIN7A expression has been previously shown to be associated with a loss of polarity in breast cancer cells as well as increased proliferation in hepatocellular carcinoma and ovarian cancer." (PMID 33726762, 2021). "In hepatocellular carcinoma, miR‐501‐3p was targeted to inhibit HCC metastasis and progression through LIN7A, a direct functional target." (PMID 40801824, 2025).
ovarian carcinoma (4 papers, 2021 to 2025). A malignant neoplasm originating from the surface ovarian epithelium. "The CASC9/miR‐758‐3p/LIN7A axis has been shown to be involved in ovarian cancer progression, accelerating tumour proliferation in vivo." (PMID 40801824, 2025). "In turn, the inhibitory effect on ovarian cancer progression following CASC9 reduction could be reversed by LIN7A overexpression." (PMID 40801824, 2025). "CASC9/miR-758-3p/LIN7A pathway was identified in ovarian cancer progression." (PMID 35427373, 2022).
breast carcinoma (3 papers, 2016 to 2023). "Among the most deregulated genes in this signature, we identified the over-expression of LIN7A - which encodes a Crumbs-complex protein - as being a specific hallmark of this particular type of breast carcinoma." (PMID 26887652, 2016). "In this IMPC-specific gene signature, LIN7A was among the most differentially over-expressed genes and the first polarity-related gene, so it appeared to be a specific hallmark of this particular type of breast carcinoma." (PMID 26887652, 2016). "The remainder of the tumor dataset, consisting of lung-, colon-, ovarian-, and breast cancers and various lymphomas tended to show low expression of both DLG2 and LIN7A." (PMID 33726762, 2021).
attention deficit-hyperactivity disorder (2 papers, 2015 to 2018). A disorder characterized by a marked pattern of inattention and/or hyperactivity-impulsivity that is inconsistent with developmental level and clearly interferes with functioning in at least two settings (e.g. at home and at school). "LIN7A encodes a protein involved with the synaptic function and neuron migration in cerebral cortex development and was associated to autism and attention deficit hyperactivity disorder." (PMID 25981335, 2015).
intellectual disabilities (2 papers, 2014 to 2024). "Matsumoto and others have found that LIN7A is key in brain development, and its deficiency may lead to intellectual disabilities and incomplete corpus callosum development." (PMID 38566986, 2024).
neuroblastoma (2 papers, 2021 to 2025). Neuroblastoma (NB) is the most common solid, extracranial childhood tumor. "In neuroblastoma, the protein encoded by DLG2‐isoform 7 positively regulates and increases the expression of LIN7A by binding to LIN7A, which significantly reduces the proliferative viability of neuroblastoma cells and increases apoptosis of tumour cells." (PMID 40801824, 2025). "Functionality of DLG2 isoforms and of LIN7A were evaluated in the 11q-deleted neuroblastoma cell line SKNAS." (PMID 33726762, 2021). "We could show that the protein encoded by DLG2-isoform 7 could bind to LIN7A, and increased DLG2-isoform 7 gene expression increased the expression of LIN7A, this reduced neuroblastoma cell proliferation and viability, with increased BAX/BCL2 ratio indicating increased apoptosis." (PMID 33726762, 2021).
autism spectrum disorder (1 paper, 2023). A spectrum of developmental disorders that includes autism, and Asperger syndrome. "Considering Lin7 in humans, disruption of cerebral cortex development by Lin7a depletion and involvement in autism spectrum disorders by genetic alteration of Lin7b has been reported." (PMID 37895291, 2023).
breast adenocarcinoma (1 paper, 2016). "LIN7A is insufficient by itself to obtain in vivo tumors when over-expressed in the non-tumorigenic MCF10A cells (data not shown), so we over-expressed LIN7A in human breast adenocarcinoma MDA-MB-231 cells (MDA-MB-231-LIN7A)." (PMID 26887652, 2016).
breast tumor (1 paper, 2018). "A recent study also demonstrated that overexpression of LIN7A facilitated proliferation, invasion, and absence of lumen formation in breast tumor cells." (PMID 29749382, 2018).
colon cancer (1 paper, 2015). "Of particular interest, three additional PDZ proteins—DLG1, CASK, and LIN7A—were detected in SW480 colon cancer cells, suggesting additional, yet to be characterized, ADRA1D complexes exist and are cell-type dependent." (PMID 26617989, 2015).
osteogenesis imperfecta (1 paper, 2024). Osteogenesis imperfecta (OI) comprises a heterogeneous group of genetic disorders characterized by increased bone fragility, low bone mass, and susceptibility to bone fractures with variable severity. "Finally, although we validated that miRNA‐29b‐3p plays a role in osteogenesis imperfecta and is able to regulate LIN7A expression in patients with osteogenesis imperfecta, we did not perform more detailed in vitro validation of the regulatory correlation between miRNA‐29b‐3p and LIN7A." (PMID 38957040, 2024).
Sepsis (1 paper, 2020). Sepsis is defined as life-threatening organ dysfunction caused by a dysregulated host response to infection. "Gene entities shared between sepsis and severe sepsis response hubs are; TDRD9 – LIN7A, GPR84 – ENTPD7, PYCT1A and ZDHHC19, CD177 – DDAH2 and RGL4, SLC16A3 – DENND3 and MBD6, MYL9 – CMTM5, ITGB3, ITGA2B, NRGN, SELP and TREML1." (PMID 32318053, 2020).
squamous cell carcinoma (1 paper, 2021). A carcinoma arising from squamous epithelial cells. "Squamous cell carcinoma (2/2) showed high DLG2 expression with low LIN7A expression." (PMID 33726762, 2021).
cancer (11 papers, 2016 to 2025). A tumor composed of atypical neoplastic, often pleomorphic cells that invade other tissues. "Lin7a is a cancer–associated protein that plays an important role in cell migration by regulating cell polarity." (PMID 39062857, 2024). "The presence of the complete L27 domain allows for the binding to LIN7A, which will control cell polarity and signaling, thus affecting cancer cell viability." (PMID 33726762, 2021). "Few studies evaluated the relationship between cancer progression and LIN7A or CAPN14 expression." (PMID 34158601, 2021). "We have also shown that LIN7A over-expression alone is sufficient to induce the absence of lumen, a traduction of an abnormal apical specification, and an increased proliferation and invasiveness of cancer cells." (PMID 26887652, 2016). "We can therefore hypothesize that AXL receptor could be activated upon LIN7A upregulation and through that mechanism could contribute to promote non-coordinated migration, leading to epithelial structure disruption and to tissue infiltration by cancer cells." (PMID 26887652, 2016). "In future, it will be interesting to identify the key downstream signaling pathways of LIN7A in HCC cells and their relevance to cancer metastasis and progression." (PMID 29749382, 2018).
tumor (6 papers, 2016 to 2025). "Our analysis showed that these previously established tumor types in which LIN7A is oncogenic or disruptive tended to cluster with low DLG2 expression." (PMID 33726762, 2021). "As a crumbs-complex polarity gene, LIN7A was particularly analyzed given that polarity deficiency is recognized as an essential step of the EMT progression and as a hallmark of tumor invasion and metastasis." (PMID 29749382, 2018). "Knockdown of LIN7A in PLC/PRF/5-anti-miR-501-3p cells (1.17 ± 0.20 cm3) led to a significant decrease in tumor volume compared to controls (3.08 ± 0.34 cm3), reversing the promoting effect induced by miR-501-3p loss in PLC/PRF/5 cells." (PMID 29749382, 2018). "The roles of miR-501-3p-LIN7A signaling on modulating tumor growth and metastasis were examined in vivo." (PMID 29749382, 2018). "LIN7A was previously known as a crumbs-complex polarity gene that could regulate tumor progression." (PMID 29749382, 2018). "Although we did not observe any phosphorylation of epidermal growth factor receptors (EGFRs) in our model, it is possible that LIN7A over-expression in IMPC increases proliferation and invasion in this particular tumor type through the activation of another tyrosine-kinase receptor." (PMID 26887652, 2016). "A weak linear relationship could be established between DLG1 and LIN7A, however no distinct tumor clusters could be formed." (PMID 33726762, 2021).
LIN7A also shares sentences with these, for which no sentence is quoted: autism (2 papers); schizophrenia (2); type 2 diabetes (2); acute myeloid leukemia (1); bacterial infection (1); cardiovascular diseases (1); coronary artery disease (1); dyslipidemia (1); infection (1); lymphoma (1); neurodegenerative disease (1); Obesity (1).